HGF (hepatocyte growth factor)
Diseases named in the same sentence as HGF in open-access papers (continued):
Sharing a sentence is not in itself a finding about the gene and the disease.
melanoma (continued). "Only MET and GAB1 exhibited significant induction following vemurafenib or PD0325901treatment, indicating this induction may contribute to the underlying mechanism of HGF rescue and explain the unique ability of HGF to rescue BRAF mutant melanoma cells from MAPK pathway inhibition." (PMID 28147313, 2017). "In addition to revealing MDG activity for survivin in vivo, the Dct-survivin × HGF/SF hybrid strain may be suitable as an in vivo model for testing of survivin-inhibitory therapies in advanced melanoma." (PMID 28788083, 2017). "Indeed, dual blockade of MEK/BRAFV600E (with PD184352, PLX4720 or vemurafenib) and MET (with crizotinib, SU11274 or MET-specific siRNA) resulted in reversal of drug resistance and reduced the proliferation of melanoma cell lines, which was restored by exogenous HGF." (PMID 24920406, 2014). "In vivo, we used the HGF transgenic mouse model of UV-induced melanoma to demonstrate that topical treatment with l-selenomethionine results in a significant delay in the time required for UV-induced melanoma development, but also increases the rate of growth of those tumors once they appear." (PMID 23470450, 2013). "While the melanoma-derived cell lines derived from HGF+ × [m1m2]+/− mice exhibited greater motility/invasion and genomic instability than their HGF+-derived counterparts, it remains to be determined whether one or both of these phenotypes are metastasis-suppressing functions." (PMID 22699362, 2013). "HGF/MET-dependent nitric oxide release by neutrophils promotes cancer cell killing in many tumors, including fibrosarcoma, colon cancer, lung cancer, melanoma, and hepatocellular carcinoma." (PMID 40564191, 2025). "As an example, the hepatocyte growth factor (HGF)/c‐Met signalling axis has been found to induce ROS production to stimulate epithelial‐mesenchymal transition (EMT) and metastasis in malignant melanoma cells." (PMID 40990316, 2025). "Specifically, augmented expression of b-FGF, HGF, SCF, and VEGF by melanoma CAF respect normal fibroblasts confirming the pro-mitogenic attitude of melanoma-associated fibroblasts." (PMID 37762344, 2023). "Our result was contradictive with some published studies, in which expression of HGF and its receptor c-MET has been reported to be increased in lung, colon, breast, thyroid, renal carcinoma, melanoma and various sarcomas." (PMID 37828456, 2023). "Activated CAFs can trigger melanoma progression and resistance to BRAF/MEK inhibitors via the release of soluble molecules including neuregulin 1 and hepatocyte growth factor (HGF) as well as fibronectin." (PMID 37370757, 2023). "Studies on MACC1 expression and its functional roles in melanoma are sparse, despite the known mechanistic link between MACC1 and HGF/MET signaling and their critical roles in inducing metastasis." (PMID 37496665, 2023). "The role of HGF/MET signaling and expression of MET in melanoma has been studied more extensively than MACC1." (PMID 37496665, 2023). "We were able to confirm the expression of the MET protein in both melanoma cell lines, and we demonstrated MET activation by its ligand, HGF, through phosphorylation, in Western blot analysis." (PMID 37104404, 2023). "In addition to its pro-invasive role, stromal-derived HGF has been reported to promote the adhesion of CRC cells to endothelial cells, facilitating metastasis as well as to underlie the resistance mechanisms to RAF inhibitors in a melanoma model and to EGFR targeting in different cancer types." (PMID 36010567, 2022). "It has been shown that the low oxygen concentration decreases the sensitivity of melanoma cells to vemurafenib several times, which is probably due to the increased activation of the PI3K/AKT and HGF/c-MET pathways." (PMID 35565444, 2022). "The HGF/c-MET pathway plays a key role in the proliferation, survival, metastasis, and resistance of melanoma cells to MAP kinase inhibitors." (PMID 35565444, 2022).
melanoma (continued). "Among the reported mechanisms involved, are increased HGF release by host fibroblasts and the promotion of matrix production and remodeling leading to elevated integrin β1/FAK/SRC signaling in melanoma cells." (PMID 35440004, 2022). "In melanoma bearing mice, PMN-MDSC have been shown to produce hepatocyte growth factor (HGF) and transforming growth factor (TGF)-β that stimulate epithelial to mesenchymal transition (EMT) and dissemination of tumor cells." (PMID 33578808, 2021). "In a spontaneous mouse model of melanoma, PMN-MDSCs recruited to tumors induced EMT by releasing TGF-β and hepatocyte growth factor (HGF)." (PMID 34576042, 2021). "Preclinical studies have shown that enhancement of HGF/c-MET activity can increase the proliferation of melanoma cells 51, increase the invasive ability of melanoma cells 52, 53 and protect melanoma cells from apoptosis." (PMID 33746605, 2021). "Contrary to melanocytes, it is a well-known fact that melanoma cells have the ability to express c-MET and also to release HGF, thus activating c-MET in an autocrine fashion." (PMID 34885093, 2021). "In particular, upon activation by melanoma cells, fibroblasts were shown to produce growth factors like insulin-like growth factor-1 (IGF-1) and HGF." (PMID 34067929, 2021). "CAF-derived HGF activates the receptor MET and its downstream pathways MAPK and PI3K/AKT signalling in melanoma cells and leads to immediate resistance to RAF inhibition." (PMID 34067929, 2021). "Along these lines, mitogenic and pro-inflammatory signals coming from hepatocyte growth factor (HGF) and tumor necrosis factor-alpha (TNFα), respectively, upregulate CD73 expression in melanoma cell lines that were unmethylated." (PMID 33430239, 2021). "In melanoma bearing mice, in fact, PMN-MDSCs induce EMT by releasing TGF-β and hepatocyte growth factor (HGF); moreover EMT was finely tuned by MDSC-secreted factors such as TGF-β release in combination with high amount of NO in nasopharyngeal carcinoma." (PMID 32133298, 2020). "Dysregulation of the HGF/MET signaling pathway has been demonstrated in a wide range of malignancies, including malignant melanoma." (PMID 32659961, 2020). "As another example of paracrine signaling between CAFs and tumor cells, the hepatocyte growth factor (HGF) is secreted by the stroma upon treatment with BRAF or EGFR inhibitors, conferring resistance to melanoma and NSCLC cells, respectively." (PMID 33291749, 2020). "For instance, specific secretion of HGF and neuregulin (NRG)-1 by fibroblasts upon exposure to vemurafenib -a BRAF inhibitor-was reported in melanoma." (PMID 33553157, 2020). "Hepatocyte growth factor (HGF) secretion by CAFs activates the RTK MET and the MAPK and PI3K/AKT pathways in melanoma cells, defining HGF secretion by local fibroblasts as an innate mechanism of resistance." (PMID 32466585, 2020). "In the same line, fibroblast-secreted HGF activates both the MAPK and PI3K/AKT pathways contributing to BRAF-targeted therapies' primary resistance in melanoma and in a subset of colorectal and glioblastoma cancer cells." (PMID 33553157, 2020). "In summary, we suggest that blocking HGF signaling with SN and CAP can overcome the EMT phenomenon in melanoma cells." (PMID 31126298, 2019). "The mechanisms behind the protective activity of HGF include upregulation of c-MET expression by MITF-M, a transcription factor of melanocytes and melanoma cells." (PMID 30513872, 2018). "As their expression is downregulated in melanoma, mainly by epigenetic silencing, the c-MET level is increased, leading to the enhancement of HGF/c-MET signaling." (PMID 30513872, 2018). "HGF, through the activation of the MAPK/ERK pathway, induces the expression of fibronectin and its extracellular assembly on the surface of melanoma cells, which enhances their metastatic potential." (PMID 30513872, 2018).
melanoma (continued). "From an opposite perspective, the role of the HGF/c-MET pathway in the progression of several tumors, including melanoma, stimulates research towards the development of inhibitors of this pathway." (PMID 30513872, 2018). "Foretinib (EXEL-2880) also inhibits HGF-driven migration and invasion of murine B16F10 melanoma cells (value IC50 of 21 nmol/L)." (PMID 29455657, 2018). "Dissimilar to melanocytes, melanoma cells not only express c-MET, but also release HGF, thus activating c-MET in an autocrine manner." (PMID 30513872, 2018). "This suggested c-Met inhibition as a promising therapeutic option for HGF producing, c-Met TKI sensitive tumors in melanoma patients." (PMID 29455657, 2018). "Specifically, hepatocyte growth factor (HGF), the cognate ligand for the RTK MET, has been shown to convey resistance to vemurafenib and a related analog, PLX4720, in BRAF mutant melanoma cell lines." (PMID 28147313, 2017). "In this study we observed a dominant role for the HGF/MET axis in mediating resistance to BRAF and MEK inhibitors in models of BRAFV600E and NRAS mutant melanoma." (PMID 28147313, 2017). "Here we tested the ability of HGF to rescue cells from dabrafenib, a selective BRAF inhibitor, approved for the treatment of BRAFV600E mutant melanoma, with similar clinical efficacy as vemurafenib but a differentiated safety profile." (PMID 28147313, 2017). "However, the migration potential of both cell lines were strongly enhanced in the presence of 40 ng/ml HGF compared to the 20% FBS alone (p < 0.001), underlining the need of factors, typically present in tumour microenvironment known to promote migration of melanoma cells." (PMID 28125999, 2017). "The positive correlation of HGF, MET, and VEGF-A expression and PLX4720 EC50 indicated that hypoxia-driven upregulation of these genes results in increased resistance to PLX4720 in melanoma." (PMID 28453553, 2017). "Another important finding of our study was the identification of GH regulation of the autocrine hepatocyte growth factor (HGF) and its cognate receptor MET (or c-MET) on the four melanoma cell lines supporting and adding to recent observation." (PMID 28223541, 2017). "In confirmation of that and other studies, we also found low levels of HGF and consistently high levels of MET and ERBB3 RNA in the four melanoma cell lines used in this study (Figure 5a1)." (PMID 28223541, 2017). "Using this method, we recently found that higher expression of HGF, MET, and VEGF-A genes correlates with lower sensitivity to a BRAF(V600E) inhibitor in melanoma cells." (PMID 28453553, 2017). "In line with that, MEDICA suppressed the IL-6- and HGF-activated phospho-STAT3(Tyr705) in CRC HT29 or PTC BcPAP cells, and the constitutively-active STAT3 in A375 melanoma cells." (PMID 26959890, 2016). "The most important canonical pathways associated with TE-predominant transcripts were prolactin signaling, melanoma, NOTCH, and HGF -signaling, and protein citrullination." (PMID 26681441, 2015). "In particular, although melanomas expressing mutant BRAF respond to vemurafenib, hepatocyte growth factor (HGF) secretion by peri-tumoural stromal cells correlated with resistance to vemurafenib-induced cell death." (PMID 26013123, 2015). "α-Catulin knockdown also decreased NF-ĸB activity after TNFα-, LPS-, HGF- and Serum (10% FCS) activation in Melanoma 7 cells, which is consistent with our previous finding that α-catulin is central for mediating NF-ĸB activation." (PMID 25793618, 2015). "Aberrant autocrine or paracrine stimulation of the HGF–MET axis contributes to tumorigenesis of breast cancers, osteosarcomas, melanomas and gliomas." (PMID 28548075, 2014).
melanoma (continued). "Published accounts of chemotactic invasion most often describe growth factors as the attractants—for example EGF for solid tumours, and EGF, hepatocyte growth factor (HGF), and stem cell factor (SCF)/KitL for melanoma." (PMID 25313567, 2014). "Mutations in MET have not been described in melanoma, but there is strong evidence that this RTK is involved in melanoma growth and metastases (see below: WNT pathway and HGF expression in stroma)." (PMID 24743024, 2014). "For this purpose, melanoma cell lines were exposed to various cytokines (EPO, EGF, TGF-ß1, Heregulin-α, IGF-1, HGF, SCF, NGF) and then were subjected to qPCR analysis and flow cytometry." (PMID 24489649, 2014). "More recently, HGF was reported to induce resistance to ALK selective inhibitors in EML4-ALK lung cancer and BRAF inhibitors in BRAF mutant melanoma." (PMID 23690929, 2013). "Several recent publications have demonstrated the importance of HGF/MET signaling and the microenvironment in melanoma treatment resistance." (PMID 24025166, 2013). "Locally invasive melanoma and distant metastatic phenotypes were reported in the HGF/SF-transgene Ink4aARF−/−, Tyr-N-RasQ61K INK4A−/− and in the BRaf V600E Pten−/− mouse models of melanoma." (PMID 27429258, 2013). "The ability of NM23 deficiency to confer metastatic potential in HGF-driven melanoma suggests the HGF+ × [m1m2]+/− strain may be a relevant experimental model for human melanomas that do not harbor BRAF mutations (20–40 %) and are unsuitable candidates for anti-BRAF therapies." (PMID 22699362, 2013). "In melanoma cells, p38-ATF-2-dependent expression of cyclin D1 in response to hepatocyte growth factor/scatter factor has been described." (PMID 22404972, 2012). "HGF signaling activates Ras-Erk1/2 and PI3K-AKT pathways, and Ras pathway activation has been shown to play a role in melanoma development and maintenance." (PMID 19274086, 2009). "In neoplasic melanoma cells isolated from spontaneous tumors raised in the mouse model, we identified LKB1 as one of the molecules responsive to HGF triggering." (PMID 19274086, 2009). "Moreover, activated CAFs release hepatocyte growth factor (HGF), vascular endothelial growth factor (VEGF), and fibroblast growth factor 2 (FGF2), which promote angiogenesis and activate survival pathways in melanoma cells." (PMID 40649909, 2025). "Upon binding of hepatocyte growth factor (HGF), nitric oxide is released to kill melanoma cells." (PMID 38419052, 2024). "Comparable with autocrine EGFR signalling discussed previously, autocrine c-MET/HGF signalling in disseminated cells and CTC clusters is hypothesised to contribute to the survival signalling necessary to evade anoikis during melanoma metastasis." (PMID 37181747, 2023). "Early studies indicated that the majority of melanoma tumours retain no expression of E-cadherin as a result of autocrine HGF secretion from melanoma cells activating c-Met and the MAPK and PI3K pathways resulting in E-cadherin downregulation." (PMID 37181747, 2023). "In this study, we investigated the interplay between HGF, its receptor c-met, and an ROS source (Nox4) in early, late, and nonmetastatic melanoma patients, looking at cellular ROS modulation through the inhibition of HGF/c-met and Nox4 in vitro." (PMID 37189846, 2023). "In many cases, melanoma patient DC secreted much lower levels of analytes than HD, regardless of clinical outcome (HGF, IL-12p70, TNFA)." (PMID 37938561, 2023). "In contrast to lung metastasis, in brain metastases of melanoma, besides TERT, amplifications of HGF (hepatocyte growth factor) and MET genes have been found, indicating the presence of a possible autocrine loop of signaling, offering a potential target therapy option for this type of metastasis." (PMID 35628196, 2022). "One of the proteins secreted by tumor-associated stromal cells, the activity of which may promote the resistance of melanoma cells to inhibitors of the MAP kinase pathway, is the hepatocyte growth factor." (PMID 35565444, 2022).
melanoma (continued). "Metastasis is further supported through increased epithelial–mesenchymal transition induced by MDSC, which has been reported to be dependent on TGF-β, Epidermal growh factor and hepatocyte growth factor (EGF, and HGF) signaling pathways in a melanoma mouse model." (PMID 33917501, 2021). "Dysregulation of HGF and/or MET expression are both observed in several tumors including melanoma." (PMID 33918490, 2021). "Current studies have shown that the metastasis of melanoma is related to the expression of certain genes and the activation of certain pathways, such as ABCB5 expression, lncRNA KCNQ1OT1, the MMP-9 signaling pathway, and the HGF-MET signaling pathway." (PMID 34582363, 2021). "In this study we investigated the first point, starting from a larger view, analyzing Nox4 and c-met expression in early, late and non-metastatic melanoma patients, then focusing on cellular ROS modulation by HGF/c-met and Nox4 inhibition in vitro." (PMID 33451139, 2021). "Crizotinib was not tested for its efficiency in melanoma but was used as an agent to validate the involvement of HGF release in the resistance to mutant-BRAF inhibitors." (PMID 33918490, 2021). "HGF is a multifunctional cytokine highly produced by mesenchymal cells, including CAFs, melanoma cells, but not by normal melanocytes." (PMID 34067929, 2021). "Co-culture systems and proteomics analysis showed that HGF secreted by fibroblasts, by interacting with its mesenchymal ephitelial transition (MET) receptor on melanoma, induced MAPK and PI3K pathways’ activation, thereby promoting resistance to RAF inhibition." (PMID 33036192, 2020). "In non-small cell lung cancer (NSCLC), IL-6 induces EMT, resulting in cisplatin resistance, while melanoma circumvents BRAF inhibition by reactivating downstream pathways (i.e., MAPK, PI3K-AKT) through c-Met activation via CAF-derived HGF (Hepatocyte Growth Factor)." (PMID 32957515, 2020). "Intriguingly, HGF seemed to be subjected to aberrant splicing events, as evinced by the multiple and high molecular weight, diverse size PCR bands (asterisks) observed in BCC and melanoma specimens." (PMID 30795533, 2019). "A new approach toward abrogating the HGF/c-MET signaling pathway using CAP and the SN could provide a novel strategy during the treatment of melanoma." (PMID 31126298, 2019). "Additionally, PMN-MDSCs can promote EMT in melanoma cells through activation of the TGF-β, epidermal growth factor (EGF) or hepatocyte growth factor (HGF) signaling pathways, leading to enhanced metastasis." (PMID 30200242, 2018). "Dissimilar to melanocytes, melanoma cells not only express c-MET, but also HGF." (PMID 30513872, 2018). "Among 18 melanoma cell lines analyzed, four displayed complete HGF-induced rescue, six partial and for eight melanoma cell lines addition of HGF did not affect melanoma cell response to vemurafenib." (PMID 30513872, 2018). "It has been demonstrated that c-Met can be constitutively active in melanoma cells without exogenous HGF stimulation." (PMID 30513872, 2018). "HGF can be bound by surface adhesion molecule CD44, which facilitates its presentation to c-MET, and HGF binding to c-MET upregulates the expression of the CD44v6 isoform in melanoma cells." (PMID 30513872, 2018). "In this study, stromal or parenchymal HGF immunoreactivity has been evaluated as a biomarker for melanoma response to RAF inhibitors, and the results were not unambiguous." (PMID 30513872, 2018). "HGF, c-MET and soluble MET (s-MET) are considered as biomarkers for melanoma, and they may provide a way to evaluate the response to therapy." (PMID 30513872, 2018). "In another study, the evaluation of patients did not provide satisfactory results to validate HGF as a biomarker for melanoma response to targeted therapies." (PMID 30513872, 2018).